LOX (lysyl oxidase)
Diseases named in the same sentence as LOX in open-access papers (continued):
Sharing a sentence is not in itself a finding about the gene and the disease.
cancer (continued). "The correlation between high LOX activity and cancer metastasis is strong enough that upregulated LOX activity can be used as a diagnostic marker for the severity of cancer in patients." (PMID 28110559, 2017). "Emerging evidence has implicated a pivotal role for lysyl oxidase (LOX) in cancer progression and metastasis." (PMID 28947950, 2017). "It is overexpressed in aggressive cancers and higher expression of LOX is associated with higher cancer mortality." (PMID 27296552, 2016). "The risk for cancer onset in these organs is higher in the LOX 473AA genotype-carrying females than males." (PMID 27367711, 2016). "The LOX G473A polymorphism apparently elevated human sensitivity to cigarette smoking carcinogens for eliciting cancers in the lung and colon." (PMID 27367711, 2016). "The LOX G473A polymorphism has been reported to enhance human susceptibility to cancers or tumors in different organs and tissues such as lung, stomach, colon-rectum, breast, cervices, ovaries, and nervous and bone systems, etc.." (PMID 27367711, 2016). "Because LOX has been associated with aggressive cancers and metastasis, it is important to characterize the intracellular functions of LOX." (PMID 27296552, 2016). "LOX G473A polymorphism apparently elevated human sensitivity to cigarette smoking carcinogens for eliciting cancers in the lung and colon only." (PMID 27367711, 2016). "LOX downregulation significantly increases the E-cadherin level and decreases the vimentin level, which shows that LOX can cause cancer cells to favor metastatic spread, which has been demonstrated in both in vitro and in vivo experiments." (PMID 28036074, 2016). "LOX is an essential component of the CD44-Twist signaling axis, in which extracellular hyaluronan causes nuclear translocation of CD44 in the cancer cells, thus, triggering LOX transcription by associating with its promoter." (PMID 26237148, 2013). "Cancer-associated fibroblasts (CAFs) drive this excessive collagen deposition, which is further reinforced by the stiffness of the matrix itself—a feedback loop enhanced by the cross-linking enzyme lysyl oxidase (LOX)." (PMID 41149224, 2025). "The top 10 most productive countries/regions in the field of LOX associated with cancer research." (PMID 40661776, 2025). "The top 20 co-cited references in the fields of LOX associated with cancer research." (PMID 40661776, 2025). "The top 20 most productive organizations in the field of LOX associated with cancer research." (PMID 40661776, 2025). "In addition, changes in collagen cross-linking, most prominently by lysyl oxidase (LOX) has also been associated with increased cancer metastasis." (PMID 35859899, 2022). "The association of LOX expression in different cancers was evaluated in earlier studies." (PMID 35054220, 2021). "The decreased expression of LOX can lead to diseases such as myocardial ischemia, cutis laxa, and Menkes syndrome, while its overexpression can be associated with atherosclerosis, pulmonary fibrosis, and cancer progression." (PMID 33669630, 2021). "Increased LOX levels may be associated with poor prognosis in different cancers, especially in patients with ER-negative breast cancers." (PMID 33271772, 2020). "It indicates that LADC cancer cells may undergo EMT to increase migrating ability to potentially drive cancer cells to invade surrounding tissue by secreting ECM remodeling-associated protein LOX." (PMID 31217907, 2019). "As CD8+ T cells have been implicated in cancer progression, one interesting avenue may be to evaluate the effects of this LOX/βAPN treatment on local T cell responses." (PMID 31069295, 2018). "Since we found LOX to be associated with microtubules in mitotic cells, we postulated that LOX may be important in determining the sensitivity of cancer cells to chemotherapeutic agents that target microtubules." (PMID 27296552, 2016).
cancer (continued). "It is reported that LOX can be disseminated into distal target organs via circulation to mobilize bone marrow derived cells (BMDCs) to distal sites, and to create pre-metastatic niche, as evidenced by consistent correlation between increased LOX expression and higher cancer metastasis risk." (PMID 24338768, 2014). "Loss of LOX expression has been reported in a variety of human cancers." (PMID 23750284, 2013). "In addition to these signaling pathways, other H2O2-mediated mechanisms could be implicated in LOX effects since these reactive oxygen species have been shown to modulate other cancer progression-related events in different experimental models." (PMID 33669630, 2021). "Nevertheless, LOX can also display antitumor effects in certain cancers, with its metabolic by-products potentially counteracting oncogenesis." (PMID 40661776, 2025). "In bone, LOX-mediated collagen crosslinking modifies tissue rigidity, promoting cancer cell invasion and evasion from dormancy." (PMID 41465319, 2025). "Beyond these well - established roles, studies have also explored the potential of LOX in cancer biology." (PMID 40661776, 2025). "LOX, for instance, modifies the extracellular matrix to facilitate cancer cell invasion, while CXCR4 promotes the migration of cancer cells to distant sites." (PMID 40563999, 2025). "Due to its contribution to cancer development and invasion, as well as therapy resistance, LOX inhibition has gained a lot of attention as a potential therapeutic target." (PMID 40227764, 2025). "This review is primarily aimed at researchers in the fields of cancer and the lysyl oxidase (LOX) family." (PMID 40786111, 2025). "These include delving into the interactions between LOX and the extracellular matrix during cancer metastasis and invasion, as well as exploring related gene regulatory pathways." (PMID 40661776, 2025). "Elevated LOX expression has been observed in various cancers, where it promotes ECM stiffening and the formation of a pro - tumorigenic niche." (PMID 40661776, 2025). "Concerning cancer cell lines, the expression of LOX, LOXL1, LOXL2, LOXL3 and LOXL4 was highest in GBM, GBM, GBM, SKCM and PAAD, while lowest in CLL, CLL, LCML, DLBC and CLL, respectively." (PMID 40179101, 2025). "ECM stiffening and collagen cross-linking, driven by matrix metalloproteinases (MMPs) and lysyl oxidases (LOX), create a microenvironment that promotes cancer cell adhesion, invasion, angiogenesis, and immune evasion." (PMID 40149289, 2025). "Multiple studies have suggested that many stages of cancer development including primary growth, angiogenesis, metastasis, and invasion are influenced by LOX." (PMID 40464853, 2025). "YAP1 has been found to be enriched in the LOX promotor region in a cancer cell line, suggesting a direct effect of YAP1 on LOX expression." (PMID 40753090, 2025). "Lysyl oxidase (LOX) was shown to mediate hypoxia-induced metastasis and is secreted in a dose-dependent manner in response to ionizing radiation in a range of cancer cell types." (PMID 40497995, 2025). "LOX, activated by BMP-1, causes stiffening of the matrix and enhances the invasive and metastatic properties of cancer cells." (PMID 39792296, 2025). "Apart from these pathways, genes like COX-2 and LOX are identified and reported that they induce metastasis as well as cancer-supporting mechanisms." (PMID 39372197, 2024). "Along with the COX-2 gene, the LOX gene plays a vital role in inflating cancer cell proliferation, angiogenesis, and metastasis." (PMID 39372197, 2024). "Another key purpose of mathematical models in biology is in elucidating unexplained processes, for example, the role of the ECM remodeling enzyme LOX during cancer cell migration." (PMID 38495620, 2024). "All ECM components, including collagen fibers and enzymes such as MMPs and LOX, are modeled using PDEs, with cancer cells modeled as discrete agents." (PMID 38495620, 2024).
cancer (continued). "In vivo, CAFs secrete growth factors that enhance metastatic advancement of cancer cells, and they synthesize collagen and the collagen cross-linker (LOX), both of which stiffen the ECM and reshape the ECM’s constitution and organization." (PMID 38397421, 2024). "For another example, the copper-dependent amine oxidase LOX promotes cancer cell invasion and migration." (PMID 39430913, 2024). "Lysyl oxidases (LOX), which are recognized as potent regulators of structural alterations in healthy connective tissue, fibrotic conditions, and cancer, are critical in the process of tumor seeding." (PMID 39154307, 2024). "Taken together, there is a growing body of evidence in the cancer literature that LOX directly impacts the growth and survival of tumors; however, its role in homeostasis is still underappreciated." (PMID 39766266, 2024). "By distinguishing crosslinked and randomly oriented ECM fibers, the model reproduces the enhanced migration of cancer cells in the presence of LOX-induced crosslinking." (PMID 38495620, 2024). "The dysfunction of copper-containing secretory enzymes, including superoxide dismutase 3 (SOD3) and lysyl oxidase (LOX), profoundly impacts cancer metastasis by promoting angiogenesis, epithelial–mesenchymal transition, and cancer cell invasion." (PMID 39430913, 2024). "Antileukoproteinase 1 increases the expression of cyclin D1 gene, decreases the tumor-suppressor gene lysyl oxidase, and protects progranulin, a highly expressed factor in aggressive cancers, from proteinase degradation." (PMID 36742380, 2023). "In tumors, the expression and activity of LOX undergo changes, and cancer cells reshape the extracellular matrix by secreting LOX, creating an environment more conducive to cancer cell metastasis." (PMID 37427098, 2023). "For instance, drugs that inhibit the collagen cross-linking enzyme lysyl oxidase (LOX) can suppress cancer growth in animal models." (PMID 36821520, 2023). "Triggers ROS storm, GSH depletion, GPX4 inactivation, and LOX catalysis, promote ferroptosis in cancer cells and enhance IFNγ and AA action." (PMID 38288118, 2023). "For ECM processing proteins, LOX was consistently downregulated across all experiments in premetastatic, cancer-conditioned groups versus controls." (PMID 37903851, 2023). "Immune-cell phenotype has been implicated in these studies as a driving force in regulating cancer development and possibly LOX expression." (PMID 37298359, 2023). "An abnormal arachidonic acid metabolic pathway is mainly due to the activation of the COX and LOX pathways, which further affects the occurrence of inflammation and cancer." (PMID 36875110, 2023). "Immune modulations in the context of LOX and cancer so far have been primarily documenting elevated expression levels of increased LOX enzyme activity and its relationships to increased tissue stiffness due to increased collagen cross-linking and fibrosis." (PMID 37298359, 2023). "By contrast, increased LOX enzyme activity derived from LOX or other LOX gene family members, such as LOXL2, promotes cancer and is associated with poor clinical outcomes." (PMID 37298359, 2023). "LOX inhibitors decrease cancer cell proliferation in both in vivo and in vitro experiments and cause death through mitochondrial induction." (PMID 37894369, 2023). "The nano-platform can induce ROS storms, depleting GSH, inactivating GPX4, and catalyzing LOX to promote irreversible cancer cell immunogenic ferroptosis." (PMID 38288118, 2023). "Lysyl oxidase (LOX) was found to be overexpressed in aggressive cancers and related to MMPs and TIMPs by regulating SNA12 expression." (PMID 36120433, 2022). "This is consistent with other EMT pathway genes in the skin; COMP, CTHRC1, ECM2, FBN1, LOX, and SPARC were all upregulated in samples with a mutation in a cancer gene." (PMID 36531005, 2022).
cancer (continued). "Our results confirm that chemotherapy induces rapid ECM remodeling in the lungs in an LOX-dependent manner, thereby enhancing cancer cell seeding and metastasis." (PMID 34666995, 2022). "Specifically, LOX/LOXL proteins are secreted by cancer cells to increase collagen linearization and tissue stiffness, promoting metastatic dissemination, and to form a premetastatic niche in a distant site." (PMID 36291728, 2022). "In this regard, MMP2 is well-known to be upregulated in a variety of cancers, suggesting a possible post-translational control of altered LOX enzyme activity or specificity in a cancerous microenvironment." (PMID 35563478, 2022). "LOX secretion by hypoxic cancer cells contributes to the formation of a premetastatic niche and promotes cancer cell seeding in distant organs by enhancing the recruitment of myeloid cells." (PMID 34666995, 2022). "LOX antibody-conjugated liposome was used for cancer-targeting drug deliverly because cancer cells secrete LOX during EMT." (PMID 35174090, 2022). "Induction of LOX-PP expression by the adenoviral vector reduced cancer cell migration and hampered the expression of angiogenic factors MMP2 and MMP9." (PMID 35563478, 2022). "Redundancy is more likely to occur in a cancer setting due to the plasticity and adaptive nature of tumors; therefore, a pan-lysyl oxidase inhibitor is generally a better approach." (PMID 35205728, 2022). "Copper also promotes the ability of cancer cells to metastasize, through the activation of LOX/LOXL proteins and of the phosphotyrosine-binding protein MEMO1 (Mediator of ErbB2-driven cell motility)." (PMID 36291728, 2022). "The first generations of lysyl oxidase inhibitors have shaped the numerous clinical trials that are currently underway in cancer and fibrosis." (PMID 35205728, 2022). "High expression of LOXL1 in cancer-associated fibroblasts (CAFs) has been shown to enhance NSCLC tumorigenicity, while increased LOX activity also helps promote increased invasion and migration of NSCLC." (PMID 35205728, 2022). "In each cg site, the methylation level of LOX in primary GC is lower than that in para-carcinoma samples." (PMID 36202905, 2022). "ANGPTL4 facilitates the extravasation of cancer cells, and LOX increases the migratory and invasive capacities of cells by activating the focal adhesion kinase (FAK)/AKT pathway." (PMID 34575983, 2021). "Recently, preliminary evidence of functionalizing the surface of poly(lactic-co-glycolic acid) PLGA-nanoparticles with a LOX-blocking antibody demonstrated promising results in suppressing cancer cell growth." (PMID 33658580, 2021). "Potent fibrogenic signaling effectors such as TGF-β1 have been shown to be regulators of LOX expression in diseases such as cancer." (PMID 33513979, 2021). "CAFs can produce large quantities of ECM molecules to remodel stroma, and LOX expression and collagen content have been observed to be clinically elevated in various malignant tumors." (PMID 34930321, 2021). "LOX is a secreted enzyme; hence, LOX detection was performed in the conditioned media of these cancer cells." (PMID 34572752, 2021). "The non-cellular compartment of the TME, such as the collagen cross-linking enzyme LOX and the metalloproteases MMPs, are also being considered as a target for cancer treatment." (PMID 34200480, 2021). "Clusters 0, 1, 2, 3, 4, 5, and 6 show expression of classical cancer-associated fibroblast (CAF) markers (FAP, PDGFRA, LOX, and metalloproteinases)." (PMID 34921143, 2021). "In this work, the impact of LOX/LOXL enzymes in cancer progression and the state of the art of the development of inhibitors are reviewed." (PMID 33669630, 2021). "Although the clinical use of BAPN has been impeded by concerns regarding toxicities, other strategies to inhibit LOX in cancer and fibrotic disease patients are currently ongoing." (PMID 34106045, 2021).
cancer (continued). "Results of our study indicate potential benefits for the use of LOX inhibitors alone or with anti‐angiogenic drugs for old patients who are at the early stages of cancer to prevent its invasion." (PMID 34617419, 2021). "The color and extinction spectra of LS-AuNPs in solution were monitored after the addition of conditioned media collected from LOX-high- or LOX-low-expressing cancer cells." (PMID 34572752, 2021). "Overexpression of LOX plays an important role in extracellular matrix remodeling and angiogenesis in various cancers." (PMID 34595188, 2021). "This colorimetric assay based on peptide-functionalized AuNP sensitively detects LOX secreted from various cancer cells not only in vitro but also in the tissue extract." (PMID 34572752, 2021). "In other cancers such as breast and pancreatic, higher LOX expression correlates with promotion of metastasis, induction of chemoresistance and poor survival." (PMID 33513979, 2021). "There has been little research thus far examining the use of BMP1 inhibitors in combination with chemotherapeutics to specifically treat LOX/LOXL1 overexpressing cancers." (PMID 33513979, 2021). "We demonstrated that LS-AuNPs are capable of the sensitive detection of LOX after the direct addition of LOX and in cancer cells with different levels of LOX secretion." (PMID 34572752, 2021). "This LOX inhibitor has shown anticancer properties in several in vitro and in vivo models of different cancer types." (PMID 33669630, 2021). "These peptides reduced activity of extracellular LOX from human umbilical vein endothelial cells (HuVEC) conditioned media, but in vitro and in vivo studies in cancer have yet to be performed." (PMID 33513979, 2021). "Cancer induced changes in the activity of these processing proteinases likely has a knock-on effect on LOX and LOXL1 collagen cross-linking activity." (PMID 33513979, 2021). "A positive correlation between FOXC1 expression and lysyl oxidase (LOX) expression was established in NSCLC patient samples wherein FOXC1 activated LOX transcription to drive cancer progression through the FOXC1-LOX axis." (PMID 34540690, 2021). "HIF-1α-induced expression of LOX typically causes stiffening of the ECM in cancer, thereby allowing cancer cells to easily metastasize." (PMID 34583752, 2021). "The elevation of LOX expression has been found in many malignant tumors and correlates with enhanced cancer cell proliferation, metastasis, and angiogenesis in the TME." (PMID 34930321, 2021). "We investigated the potential use of LS-AuNPs to determine the levels of LOX released from various cancer cells." (PMID 34572752, 2021). "In the formation of premetastatic niches, cancer cells secrete the LOX protein to stimulate collagen cross-linking and fibronectin synthesis." (PMID 33271772, 2020). "Despite the relatively well-established roles of LOX in stimulating cancer metastasis, its contribution to chemoresistance in TNBCs has not yet been reported." (PMID 32415208, 2020). "Eicosanoid which produced by arachidonic acid (AA) with lysyl oxidase (LOX) metabolism is related to cancer." (PMID 33265939, 2020). "These analyses confirmed allele-specific hypomethylation of mutant alleles compared to WT alleles in cancer cell line models with C228T or C250T TERT promoter mutations, namely, LOX-IMVI, M14, SNB19 and TSU-PR1." (PMID 32468444, 2020). "Of the LOX family interactome, 17.5%, corresponding to 56 genes, including the LOX gene, belong to the “Cancer-related condition” class defined in Reactome FIViz." (PMID 33383846, 2020). "Another interesting feature of the LOX family interactome is the over-representation in the network of the transcription factor SP1, which is over-expressed in many cancers in keeping with the role played by LOX and LOXLs in these diseases." (PMID 33383846, 2020). "The members of the lysyl oxidase (LOX) family initiate covalent cross-linking of the extracellular matrix and contribute to cancer progression." (PMID 33383846, 2020).